RNU4-16P (RNA, U4 small nuclear 16, pseudogene)
Gene: Small nuclear RNA gene on chromosome 7 (95,098,227 to 95,098,367, forward strand). Ensembl gene ENSG00000201607.
Homologues: Orthologues: chimpanzee U4 (99% identical), macaque U4 (91% identical), rabbit U4 (62% identical), dog U4 (60% identical), dog U4 (51% identical), rat LOC120096088 (50% identical). Paralogues in human: RNU4-7P (84% identical), RNU4-13P (83% identical), RNU4-67P (83% identical), RNU4-44P (82% identical), RNU4-42P (81% identical), RNU4-68P (79% identical), RNU4-76P (79% identical), RNU4-8P (79% identical), RNU4-80P (78% identical), RNU4-23P (77% identical), RNU4-84P (77% identical), RNU4-92P (77% identical), and 82 more.